CD80 (CD80 molecule)
Diseases named in the same sentence as CD80 in open-access papers (continued):
Sharing a sentence is not in itself a finding about the gene and the disease.
lymphoma (24 papers, 2010 to 2025). A malignant (clonal) proliferation of B- lymphocytes or T- lymphocytes which involves the lymph nodes, bone marrow and/or extranodal sites. "For this purpose, Rag2– γc– mice (n = 22) were intravenously injected with CD19/CD80/CD86-positive Raji lymphoma cells and treated with CAR (2nd Gen) T cells, corresponding to the Kymriah product (Novartis)." (PMID 38340727, 2024). "Monoclonal antibodies targeting CD80 have entered clinical trials for the treatment of lymphoma, but the safety of CD80 as a target needs to be further investigated." (PMID 39575257, 2024). "present an “AND” switch CAR T cell construct that fully activates only when it binds to CD19 and CD80/CD86 found on lymphoma cells." (PMID 38340727, 2024). "The CML cell line KU812 expressed similar levels of CD80 as K562, whereas the Daudi lymphoma cell line expressed significantly higher basal CD80 levels." (PMID 31452512, 2019). "The expression level of CD80 was significantly lower in the lymphoma group than in the control group (P = 0.004)." (PMID 30040869, 2018). "The expression level of CD80 mRNA was significantly lower in the lymphoma group than in the control group." (PMID 30040869, 2018). "Blockade of the CD70 or CD80/86 pathways during co-culture with lymphoma cells reversed the differentiation of CD4+ cells into Tregs, and instead promoted the generation of anti-tumor Th17 cells." (PMID 25941795, 2015). "As CD80 can directly interact with PD-L1 with either immune stimulatory or inhibitory outcomes, the hierarchy and all possibility of these interactions in the various lymphoma TME need to be considered when assigning patients to ICB-based treatments." (PMID 35071240, 2021). "Interestingly, although perhaps not unexpected, this analysis also identified that hematological malignancies including lymphomas generally expressed higher levels of CD80 when compared to cell lines originating from solid epithelial cancers." (PMID 31959281, 2020). "Interestingly, low expression of CD80 was observed in canine lymphoma samples." (PMID 30040869, 2018). "IRF4 has been known to regulate the expression of costimulatory molecules (CD80/CD86) and MHC-class-II-dependent antigen presentation in multiple immune cell types, including dendritic cells, CD226+ macrophages, and lymphoma B cells." (PMID 40585371, 2025). "The role of CD80/CD86 is not yet fully clear in lymphoma, but their expression has been noted on tumor cells and/or on cells from the TME." (PMID 35071240, 2021). "Expression levels of B7-1 (CD80) and B7-2 (CD86), ligands for the activation receptor CD28 and inhibitory receptor CTLA-4 (CD152) on T cells, vary between different models and subtypes of lymphoma." (PMID 25941795, 2015). "Previous studies indicated that early lymphomagenesis in lymphomas is a process related to CD4 + T cells stimulated by H. pylori antigens, and the proliferation of B-cell gastric lymphoma is dependent on CD40-mediated signaling, Th2 activities, co-stimulatory CD80, and CD86." (PMID 34980267, 2022). "Moreover, we performed multicolor flow cytometry to examine the role of miR130b in immune checkpoint genes including PD-L1, CD80, 4-1BBL, LAG3, TIGHT, TIM3, and VISTA on lymphoma cells in the miR130b-overexpressing DB co-culture system and miR130b-knockdown OCI-ly10 co-culture system." (PMID 35301282, 2022). "These analyses suggested that co-expression of high levels of CD80 and PTK2 transcript occurs preferentially in cancer cell lines originating from patients with Burkitt’s Lymphoma, Hodgkin’s Lymphoma, Chronic Myeloid Leukemia, and Diffuse Large B-cell (DLBCL) Lymphoma." (PMID 31959281, 2020). "In the murine A20 lymphoma model, cells express no detectable surface CD80." (PMID 25941795, 2015).
lymphoma (continued). "CD80 may also play a role in regulation of normal and malignant B-cells and may be constitutively expressed on NHL, making it an attractive target for lymphoma therapy." (PMID 22084681, 2010). "Up-regulation of CD80 and CD86 may enhance a T cell response to CLL and lymphoma." (PMID 22084681, 2010). "CD80 and/or CD86 are expressed on the surface of these B cells from most DLBCL patients, although we could not differentiate between lymphoma and other B cells." (PMID 38340727, 2024).
colitis (21 papers, 2009 to 2025). Inflammation of the colon. "In contrast to acute and chronic DSS colitis, T cell-associated transcription factors or inflammatory cytokines were not altered, but we detected slightly increased mRNA levels of Il6, CD80, and Cd86 in PTPN2fl/flxCD11cCrexRAG−/− mice after naïve T cell transfer." (PMID 34201918, 2021). "In a model of bacterial infection and dextran sodium sulfate –induced colitis, the involvement of active PD-L1+ CD80+ eosinophils in host defense and immune response was shown to be dependent on IL-33 and IFN-γ signaling." (PMID 40050933, 2025). "Based on these observations, we investigated the impact of Fn in a TNBS-induced murine colitis model and found that Fn markedly increased CD80+CD86+ DCs in the colonic LP and induced a Th17/Treg imbalance in MLNs." (PMID 41567217, 2025). "Type 2 eosinophils expressed high levels of CD101, compatible with lung iEos, whereas type 1 eosinophils expressed CD80 and PD-L1, resembling active eosinophils from mice with colitis." (PMID 40050933, 2025). "Peritoneal macrophages from colitis mice treated with cADSCs primed with each condition were isolated and the frequencies of F4/80+ CD80+ proinflammatory M1 macrophages and F4/80+ CD206+ anti-inflammatory M2 macrophages were determined using flow cytometry." (PMID 39176394, 2024). "Both naive cADSCs and cADSCs primed with any condition reduced F4/80+ CD80+ M1 macrophages, which were drastically increased by colitis induction, but cADSCs primed with TNF-α+IFN-γ or colon homogenate in particular significantly and markedly reduced them." (PMID 39176394, 2024). "Frequencies of CD83+ and CD80+ cells in the colitis group were increased compared to the control group (p < 0.01)." (PMID 39201260, 2024). "The probiotic mixture administered to mice with colitis reduced the frequencies of CD40+ (p < 0.001), CD83+ (p < 0.01), and CD80+ (p < 0.001) cells compared to untreated colitis mice." (PMID 39201260, 2024). "Compared with the control, colitis mice and the colitis mice treated with the probiotic mixture had significant increases in the frequency of CD80+ cells (p < 0.05, p < 0.01 respectively)." (PMID 39201260, 2024). "In this study, we showed that CD40+, CD83+, and CD80+ cells were decreased in IELs of colitis mice after probiotic mixture treatment." (PMID 39201260, 2024). "To mimic the human IBD, we used an in vivo model of DSS-induced colitis and we found features of inflammation compared to control mice as revealed by CD80 evaluation." (PMID 37240299, 2023). "In line with the role of CD80+ cells in colitis, the inflammatory score was significantly lower in mice treated with anti-CD80 but was not affected in mice treated with anti-CTLA4." (PMID 25595911, 2015). "In PBLs, the frequencies of CD40+ and CD80+ cells were significantly increased in DSS-treated ERAP1+/− mice (p < 0.01) and in sulfasalazine-treated ERAP1+/− colitis mice (p < 0.05) compared to ERAP1+/− healthy controls." (PMID 40977735, 2025). "Mice with colitis showed higher frequencies of CD40+ cells (p < 0.05) and CD80+ cells (p < 0.01) in the PBL compared to controls." (PMID 39201260, 2024). "In IELs, administration of the probiotic mixture to mice with colitis also significantly decreased the frequencies of CD40+, CD83+, and CD80+ cells (p < 0.05)." (PMID 39201260, 2024). "In particular, Bifidobacterium longum alleviated dextran-sulfate-induced colitis through CD40- and CD80-mediated IL-12 production in intestinal epithelial cells." (PMID 36558497, 2022). "To begin to dissect the in vivo functional role of CD80 in colonic inflammatory carcinogenesis, we used AOM-DSS colitis as a mouse model of inflammatory colonic carcinogenesis." (PMID 25595911, 2015). "In accordance with the CLS results, macrophages (MOMA+) and activated macrophages (MOMA+ CD80+) were increased in the HFD groups and were significantly higher when HFD was combined with colitis." (PMID 22073943, 2011).
colitis (continued). "Furthermore, ERAP1+/− colitis mice exhibited higher levels of CD40+, CD80+, and CD83+ cells compared to WT colitis mice." (PMID 40977735, 2025). "In the experimental colitis model, activated DCs produce numerous pro-inflammatory cytokines including TNF-α, IL-1β, IL-6, and IL-12 and express high levels of co-stimulatory molecules including CD80 and CD86." (PMID 31286993, 2019). "Taken together, our results may highlight a novel aspect of IECs as a IL-17A-inducer in murine colitis, and that costimulatory molecules in IECs such as CD80/CD86 and CD40 may be a therapeutic target for colitis." (PMID 24255712, 2013). "Flow cytometry confirmed that the combination of colitis and HFD increased leukocyte migration and activation in the lamina propria, as seen for neutrophils, T helper (CD4+) cells, B (CD 19+) cells and activated macrophages (MOMA+ CD80+)." (PMID 22073943, 2011). "In addition, a direct pathological role for CD80 and CD86 in UC has been postulated, and blockade of CD80 suppresses colonic inflammation in a murine colitis model." (PMID 20360984, 2010). "The administration of T. halophilus to DSS-induced colitis mice significantly decreased the frequencies of CD80+ cells more than in non-treated colitis mice in PBL (43.95 ± 6.50 % vs. 61.60 ± 4.38%, p < 0.01) and in IELs (61.43 ± 7.20% vs. 73.13 ± 2.67%, p < 0.05), respectively." (PMID 35741032, 2022). "Importantly, in the setting of IBD, CD80, but not CD86 blockade prevented CD4+ T cells with pathogenic potential to induce colitis in mice." (PMID 25505551, 2014).
influenza (20 papers, 2012 to 2025). An acute viral infection of the respiratory tract, occurring in isolated cases, in epidemics, or in pandemics; it is caused by serologically different strains of viruses (influenzaviruses) designated A, B, and C, has a 3-day incubation period, and usually lasts for 3 to 10 days. "This dysregulation of TNF-α and IL-6 vs. IL-10 response to influenza vaccination has been linked to the downregulation of the expression of the costimulatory molecules CD80 and CD86 by activated monocytes as a predictor of the antibody response to influenza vaccination." (PMID 28769922, 2017). "The combination of Polymyxin B MPs with MF59 in the H1N1 influenza vaccine further significantly increased CD80 expression in comparison to Polymyxin H1N1 + Polymyxin B, whereas adding Alum did not." (PMID 41441698, 2025). "Preferential induction of CD86 over CD80 in vivo has been demonstrated in a mouse model for influenza infection, in which type I IFN-mediated signals were responsible for upregulation of CD86 in B cells." (PMID 24472094, 2014). "In the influenza model, CD80 and CD86 have been analyzed primarily in their capacity to support the induction of pro-inflammatory T effector responses and the expression of pro-inflammatory mediators by the T effector cells." (PMID 25144228, 2014). "Indeed, pre-vaccination expression of costimulatory molecules, CD80 and CD86 on TLR-activated monocytes from elderly and young HIV-uninfected adults was shown to associate with vaccine responses to influenza." (PMID 33868267, 2021). "Interestingly, the activation marker CD80 expressed on Naïve B cells was negatively correlated with serological response to influenza vaccine suggesting that it could be of relevance in determining the vaccine responses." (PMID 28448963, 2017). "Recent work in a mouse model of acute influenza infection has demonstrated that MHC class I, CD80, and CD86 are all required to maintain PD-1+ TRM cells." (PMID 36189800, 2022). "Conditional deletion of CD80 and CD86 in B cells also reduced anti-influenza IgG antibody production in an infection model in vivo." (PMID 32228715, 2020). "Further, we found increased frequency of M1 (CD80+) and M1/M2 (CD80+MGL+) co-expressing macrophages in Stat2−/− mice when compared to WT during influenza-bacterial super-infection." (PMID 30337919, 2018). "A recent study has indicated that depletion of dendritic cells or blockade of CD80/86 signaling results in decreased virus-specific CD8+ T cells and impaired viral clearance during influenza infection." (PMID 22474484, 2012). "By day 7, expression of Ccl3, Cxcl9, Cd86, Il-6, Cd80, and Cxcl11 remained elevated in young adult lung in response to H1N1, while expression of Ccl5, Ccl4, and Cd40 remained elevated in response to either strain of influenza." (PMID 34829979, 2021). "By in vivo antibody-mediated blockade of CD80 or CD86 after virus clearance, we found that engagement of CD86 (but not CD80) was required for optimal recovery after influenza infection." (PMID 25144228, 2014). "We also assessed AT2s for CD80, CD86, and ICAM-1 expression and found that AT2s expressed ICAM-1, but not CD80 or CD86, both at homeostasis and after influenza infection." (PMID 34183650, 2021). "Also, we found increased frequency of M1 (CD80+), but not M2 (MGL+) single positive cells in Stat2−/− mice during influenza-bacterial super-infection." (PMID 30337919, 2018).
Obesity (19 papers, 2013 to 2024). Accumulation of substantial excess body fat. "In apparent conflict with a protective role for CD80/CD86 in obesity-associated IR, one group of investigators reported that CTLA-4-IgG1 administration improved insulin sensitivity in DIO mice." (PMID 26146464, 2015). "Given that macrophage infiltration into adipose tissue is a hallmark of obesity, tissue sections of eWAT from WT and Negr1−/− mice were prepared and stained with anti-F4/80 (pan-macrophage marker) and anti-CD80 (M1 macrophage marker) antibodies." (PMID 37187893, 2023). "The increased expression of Il1β and Cd80 underscored the shift towards a pro-inflammatory macrophage profile in WAT during obesity." (PMID 39683572, 2024). "Insulin resistance has been associated with ATM MHC II antigen presentation in murine obesity and in human CD11c+ ATMs, so we examined antigen presentation–related genes HLA-D, CD40, CD80, CD86, and ICAM1 in ATM subtypes." (PMID 34990410, 2022). "In our previous investigation, we also elucidated a homeostatic role of B7-mediated co-stimulation in diet-induced obesity using CD80/CD86 double knockout (B7 KO) mice and investigated the relevance of this process in humans with obesity and IR." (PMID 29416823, 2018). "In obesity, CD80 and CD86 gene expression have been shown to be increased in obese human and mouse adipocytes." (PMID 26146464, 2015). "Moreover, individuals with obesity and T2D had a higher proportion of immune cells expressing activation markers such as CD80, and T cells expressing CD278, which play an important role in IL-2 production and T cell proliferation." (PMID 35782930, 2022). "Adipocytes from humans with obesity had increased expression of multiple MHCII-related genes (CIITA, HLA-DPA1, CD74, CD80) in both VAT and SAT." (PMID 36153324, 2022). "A direct comparison of profiles at T1 and T3 shows a lack of remodeling within promoter and enhancer regions that regulate cytokine-signaling (TNF), myeloid cell activation (CD80), and immune effector process (HLA-DRA) in monocytes from subjects with obesity." (PMID 34195568, 2021). "While Cd86 gene expression increased following obesity, no change in Cd80 mRNA or protein expression was observed due to diet within the classical monocyte subcluster." (PMID 35618862, 2022). "In order to evaluate whether obesity affected monocytes functions we evaluated the expression of CD36, TRL-2, TRL-4 and HLA-DR, CD40, CD80/86 molecules in NW and CO." (PMID 27977792, 2016). "In the current HFD induced obesity model, the CD80’s stagnation in Lkb1-/-ATDC becomes more significant might be partially due to the higher lipid accumulation in ATDC, which suppressed the CD80 regulation pathway." (PMID 36781473, 2023). "Furthermore, within the population of macrophages with high CD206 expression, there was higher expression of CD11b, CD11c, CD32, CD80, CD86, CD163, CD192, and HLA-DR in obesity, suggesting that these macrophages were activated and shared components of both classical M1 and M2 expression patterns." (PMID 30719456, 2019).
lung carcinoma (18 papers, 2009 to 2025). "DC-based HHP lung cancer vaccine [HHP+poly(I:C)] displays significantly higher expression of CD80, CD83, HLA-DR and CD86 than control immature DC [iDC], DC pulsed with HHP-killed cells alone [HHP] or DC stimulated only with poly(I:C) [poly(I:C)]." (PMID 28187172, 2017). "DC-based HHP lung cancer vaccine exhibited higher expression of CD80 and CD83 when stimulated with CD40L-expressing A549 in comparison to DC-based HHP lung cancer vaccine incubated with non-transfected A549." (PMID 28187172, 2017). "The activation state of macrophages in the lungs has been linked to differential prognosis in lung cancer, with M2 macrophages (expressing CD206) being more permissive for cancer growth and M1 macrophages (expressing CD80) being generally protective against cancer." (PMID 29399400, 2018). "DC-based HHP lung cancer vaccine was not functionally exhausted by the first maturation stimuli with poly(I:C) as DC enhanced the expression of maturation associated molecules CD80 and CD83 and IL-12p70 production in response to LPS and CD40L." (PMID 28187172, 2017). "In fact, DCs cultivated in the presence of lung cancer patient serum have shown decreased expression of CD40, CD80, CD86, MHCII, IL1 and NFκb, similarly to the results we showed here." (PMID 34535708, 2021). "DC treated with lung cancer cell culture supernatants significantly downregulated the expression of MHC class II molecules and of the costimulatory molecules CD40 and CD80, but upregulated the inhibitory molecule PD-L1/CD274." (PMID 33066260, 2020). "The transfer of DC-based HHP lung cancer vaccine into serum containing conditions led to an increased expression of CD80 and CD83 within next 24 h compared to DC-based HHP lung cancer vaccine left in serum-free medium." (PMID 28187172, 2017). "Another genetic approach was to engineer lung cancer tumor cells with either HLA-A1 or HLA-A2 MHC molecules along with the immune costimulatory molecule, CD80." (PMID 22899945, 2012).